ICAM3 (intercellular adhesion molecule 3)
Diseases named in the same sentence as ICAM3 in open-access papers (continued):
Sharing a sentence is not in itself a finding about the gene and the disease.
cancer (23 papers, 2008 to 2025). A tumor composed of atypical neoplastic, often pleomorphic cells that invade other tissues. "Of the 23 immune-related prognostic genes identified in LUAD, 7 were reported to be associated with the progression of NSCLC or other cancers, such as ICAM3, MS4A1, and IL-16." (PMID 32209727, 2020). "Additionally genes DPYD, ABCC1, FTL and ICAM3 whose expression is shown to be associated with outcome of cancer treatment were also observed in the data set." (PMID 18782426, 2008). "Using the same pathway and CREB pathway, ICAM-3 expression favors cancer invasiveness by upregulating expression of MMP-2 and MMP-9." (PMID 40071851, 2025). "Further, we summarized ICAM3 expression in 31 cancers using the GEPIA, TIMER, UALCAN and TNMplot databases." (PMID 39991572, 2025). "Among these, ICAM3 is a crucial member, extensively studied and reported for its expression and function in both normal cells, such as in different lymphocytes, and in cancer cells." (PMID 39991572, 2025). "ICAM-3, whose secretion was up-regulated only by bEVs in U251 MG cells, drives carcinoma cell migration and invasion via the AKT pathway." (PMID 39767739, 2024). "We identified several novel candidate genes (e.g., ICAM3, CCL16, PDE3A, and PRTN3) and showed that ICAM3 mediates cancer cell stemness as well as cancer-related inflammation via Src/PI3K/AKT signaling." (PMID 33500726, 2021). "In regards to therapeutic strategies, aspirin combined with HDM inhibitors, Src/PI3K inhibitors, or ICAM3 inhibitor Lifitigrast diminished cancer progression in vivo." (PMID 32854760, 2020). "We used aspirin combined HDM (KDM6A/B) inhibitors or ICAM3 inhibitor Lifitigrast or ICAM3 downstream signaling Src/PI3K inhibitors restrained cancer progression in vivo." (PMID 32854760, 2020). "The role of ICAM3 in cancer was also widely reported in published studies, and the Akt pathway plays an important role in the impact of ICAM3 on tumors." (PMID 32854645, 2020). "YG Kim et.al reported that ICAM3 can induce the proliferation of cancer cells through the PI3K/Akt pathway." (PMID 32854645, 2020). "Our previous work established a medium-throughput siRNA screening platform to identify inflammation genes that regulate cancer cell stemness and identified several novel candidates (e.g., ICAM3)." (PMID 32854760, 2020). "ICAM3 mediates cancer cell stemness as well as cancer-related inflammation via Src/PI3K/AKT signaling." (PMID 32854760, 2020). "We selected ICAM3 since our previous studies demonstrated that ICAM mediates cancer cell inflammation and stemness." (PMID 32528119, 2020). "Our results demonstrated that the amount of ICAM3 DNA fragments in the various H3 methylation marker pull-downed DNAs decreases in all three cancer cell lines." (PMID 32854760, 2020). "Our results demonstrated that the amount of ICAM3 DNA fragments in the various H3 modification marker pull-down DNAs decreases in all three cancer cell lines." (PMID 32528119, 2020). "Our work assesses the feasibility of ICAM3 as a molecular marker for the diagnosis of human diseases and cancers, which may provide new targets for treating related diseases and cancers." (PMID 39991572, 2025). "Furthermore, in vitro and in vivo, knockdown of ICAM3 inhibits cancer metastasis, whereas ectopic expression of ICAM3 promotes cancer metastasis." (PMID 39991572, 2025). "We first summarized the expression of ICAM3 in cancer types that have been reported and studied." (PMID 39991572, 2025). "The role of ICAM3 in different human diseases, particularly in cancers, has been investigated." (PMID 39991572, 2025). "In addition to cell proliferation and dissemination, activation of this pathway by ICAM-3 also promote anti-cancer drug resistance." (PMID 40071851, 2025). "Additionally, we discuss the applications of ICAM3 in different types of cancers, providing insights into the future development of novel targeted drugs and related cancer therapies." (PMID 39991572, 2025).
cancer (continued). "Finally, in ICAM3, cancer cells mainly expressed a short protein-coding isoform, while distal cells (mainly T cells) expressed the canonical isoform." (PMID 38012143, 2023). "Our previous work proved that ICAM3 could mediate Src/PI3K signaling to promote cancer cell stemness." (PMID 32854760, 2020). "For example, P-selectin may be expressed on activated thrombocytes as well as endothelial cells, and ICAM-3 is primarily expressed on leukocytes instead of endothelial cells, unless these are located in benign or malignant tumors." (PMID 31408493, 2019). "ICAM3 may have different expressions and functions across various cancer types." (PMID 39991572, 2025). "They found that the knockdown expression of the candidate gene ICAM3 significantly inhibits the promoter activity of OCT4 and suppresses the proportion of ALDH+ cancer stem cells." (PMID 39991572, 2025). "Another important mechanism that we identified among the LR biomarkers is the stimulation of LFA-1 (encoded by ITGAL and ITGB2 genes) by ICAM (ICAM2 → ITGAL, ICAM1_ICAM3 → ITGAL, and ICAM3 → ITGB2 in 18, 11, and 8 cancer types, respectively)." (PMID 34430923, 2021). "For example, the CAMs pathway enables cancer cells to attach to the endothelium in the target organ, and the Ig-CAMs (ICAM1, ICAM3) have important roles in this process." (PMID 33413400, 2021). "In regards to therapeutic strategies, aspirin combined HDM inhibitors, ICAM3 downstream signaling Src/PI3K inhibitors, or ICAM3 inhibitor Lifitigrast prevents cancer progression in vivo." (PMID 32854760, 2020). "It is also noteworthy that, compared to ASCs-CM, hUCESCs-CM contain lower levels of factors known to participate in cancer progression, such as EGFR, FGF 4 and 9, ICAM3, IL6, IL6R, MCP3 (CCL7), MIF, sgp130 and VEGFD." (PMID 25296979, 2014). "In cervical cancer, the induction of ICAM-3 has been shown to confer radioresistance to tumour cells and anticancer drug resistance via activation of the Akt/ERK-CREB-2 signalling pathway, which induces cancer cell proliferation and reduces apoptosis." (PMID 38391953, 2024). "However, the unexpected result was that ICAM3 expression was not the same in the same cancer type, in different databases." (PMID 39991572, 2025).
tumor (22 papers, 2010 to 2025). "In the tumor microenvironment, DC-SIGN (+) dendritic cells mediate efficient tumor-associated antigen presentation to T lymphocytes via ICAM-3, a DC-SIGN-binding protein that leads to the regression of established tumors." (PMID 40612871, 2025). "Lifitegrast, a drug that disrupts the binding between LFA-1 and ICAM-3, was shown through in vitro assays and mouse models to inhibit cell migration in both tumor cell lines." (PMID 39911389, 2025). "ICAM-1, -2 and -3 are expressed by both leukocytes and endothelial cells, although only bone marrow and tumour endothelial cells can express ICAM-3." (PMID 38391953, 2024). "Among these, ICAM3 up-regulation was previously shown to be correlated with tumor staging and to mediate tumor metastasis." (PMID 34750607, 2021). "Most likely, ICAM3-Fc activates other receptors which enhance the cross-presentation of the encapsulated tumour Ag by the DC." (PMID 31083610, 2019). "In addition, it is reported that ICAM3 induced tumor metastasis through an LFA-1-ICAM3-ERM axis." (PMID 39643827, 2025). "ICAM-3 is an adhesion molecule that can interact with LFA-1 extracellularly or ezrin/radixin/moesin intracellularly, contributing to tumor metastasis." (PMID 36059515, 2022). "ICAM-3 (intercellular adhesion molecule 3, CD50) belongs to the ICAM (intercellular adhesion molecule) immunoglobulin superfamily and plays important roles in immune response and tumor development." (PMID 36033493, 2022). "The intercommunication between LFA-1 on tumour cells and ICAM-1 (or alternative ligands, ICAM-2/ICAM-3/ICAM-4/JAM-1) on other cells in the local vicinity triggers signalling through several pathways on each side." (PMID 27447568, 2016). "In addition to VEGF, ESM1 promoted MMP9, DLL4, and ICAM3 expression, indicating that ESM1 cooperated with VEGF to promote tumor development and promote bevacizumab resistance." (PMID 36428773, 2022). "In these previous studies, sets of genes associated with pathways such as apoptosis (e.g., bax, bcl-2), DNA damage repair (e.g., Ku80, GADD45, XRCC5), cell adhesion (e.g., ICAM-3), angiogenesis (e.g., HIF-1a), and tumor cell invasion (e.g., CTSL, CTSB) were identified." (PMID 20184742, 2010).
infection (4 papers, 2009 to 2024). The state of being infected such as from the introduction of a foreign agent such as serum, vaccine, antigenic substance or organism. "As a protein involved in co-stimulation, increased levels of ICAM-3 have not only been shown to increase HIV-1 transcription and viral production, but also to augment the infection of resting CD4+T cells." (PMID 27600080, 2016).
vasculopathy (1 paper, 2023). "Soluble adhesion molecule markers, such as ICAM-1, ICAM-3, and VCAM1, and inflammatory cytokine and markers like neopterin have been used as possible biomarkers of vasculopathy in JDM." (PMID 37957619, 2023).
ICAM3 also shares sentences with these, for which no sentence is quoted: liver cancer (2 papers); multiple sclerosis (2); non-small cell lung carcinoma (2); allergic disease (1); atherosclerosis (1); autoimmune disorder (1); breast adenocarcinoma (1); cardiovascular disease (1); celiac disease (1); Chagas disease (1); chronic sinusitis (1); Cluster headache (1); colitis (1); colorectal adenocarcinoma (1); depression (1); dermatofibrosarcoma protuberans (1); diffuse large B-cell lymphoma (1); fibrosis (1); gastrointestinal disorders (1); glioma (1); hepatitis C infection (1); Hypertension (1); infantile hemangiomas (1); inflammatory bowel disease (1); Insulin resistance (1); Intracranial Aneurysms (1); lymphoma (1); metastatic cancers (1); metastatic tumors (1); nasal polyps (1).
A further 10 diseases each share a sentence with ICAM3 in 1 paper.